COMP (cartilage oligomeric matrix protein)
Diseases named in the same sentence as COMP in open-access papers (continued):
Sharing a sentence is not in itself a finding about the gene and the disease.
pseudoachondroplasia (continued). "Pseudoachondroplasia (PSACH) is an autosomal dominant skeletal dysplasia resulting from mutations in cartilage oligomeric matrix protein (COMP), a large pentameric glycoprotein present in cartilage, bone, skeletal muscle, tendon and ligament." (PMID 24558358, 2014). "Mutations in the COMP gene have been linked to two human skeletal dysplasias, pseudoachondroplasia (PSACH) and multiple epiphyseal dysplasia (MED)." (PMID 22906101, 2012). "Interest in this extracellular matrix protein increased when it was recognized that mutations in COMP caused pseudoachondroplasia (PSACH) and multiple epiphyseal dysplasia (MED/EDM1)." (PMID 20421976, 2010). "Neurofibromatosis type 1 and pseudoachondroplasia are both rare autosomal dominant disorders, caused by pathogenic mutations in NF1 and COMP genes, respectively." (PMID 36890482, 2023). "Pseudoachondroplasia (PSACH) (OMIM #177,170), is autosomal dominant and results from mutation in the cartilage oligomeric matrix protein (COMP) gene." (PMID 34417863, 2021). "COMP is essential in chondrogenic growth plate development and mutations in COMP are linked to the human skeletal disorders pseudoachondroplasia (PSACH) and multiple epiphyseal dysplasia (MED)." (PMID 32984292, 2020). "The role of ER stress in GSDs might best be exemplified by mutations in COMP, matrilin-3 and type X collagen resulting in pseudoachondroplasia (PSACH), multiple epiphyseal dysplasia (MED) and metaphyseal chondrodysplasia type Schmid (MCDS), respectively." (PMID 26635999, 2015). "For example, mutations in ECM genes encoding collagen IX, matrilin-3 and cartilage oligomeric matrix protein (COMP) result in multiple epiphyseal dysplasia (MED) and pseudoachondroplasia (PSACH)." (PMID 25693198, 2015). "The intracellular retention of the mutant collagen X would lead to the retention of this second component in a similar fashion to that proposed for the role of mutant COMP in the pathogenesis of pseudoachondroplasia." (PMID 19834559, 2009). "Mutations in cartilage oligomeric matrix protein (COMP), a cartilage structural protein, cause both multiple epiphyseal dysplasia (MED) and pseudoachondroplasia (PSACH); together referred to as the COMPopathies, which result from the intracellular retention of mutant COMP to varying degrees." (PMID 41465495, 2025). "Pseudoachondroplasia (PSACH), a severe dwarfing condition characterized by impaired skeletal growth and early joint degeneration, results from mutations in cartilage oligomeric matrix protein (COMP)." (PMID 39795874, 2024). "Pseudoachondroplasia (PSACH), a short limb skeletal dysplasia associated with premature joint degeneration, is caused by misfolding mutations in cartilage oligomeric matrix protein (COMP)." (PMID 34502142, 2021). "It has been demonstrated that COMP variants are associated with multiple epiphyseal dysplasia (MED, MIM#132400) and pseudoachondroplasia (PSACH, MIM #177170) with autosomal dominant inheritance." (PMID 39415983, 2024). "Mutations in the COMP genes cause pseudoachondroplasia (PSACH) and multiple epiphyseal dysplasia (MED/EDM1)." (PMID 37082197, 2023). "In MED cases, the mutations are either on the COMP or MATN3 gene, the former also being known to cause pseudoachondroplasia (PSACH), another disease in which windswept deformity can be found." (PMID 35626880, 2022). "Numerous mutations in COMP have been identified in patients with MED and pseudoachondroplasia (PSACH)." (PMID 32686688, 2020). "Mutations in genes encoding cartilage oligomeric matrix protein and matrilin-3 cause a spectrum of chondrodysplasias called multiple epiphyseal dysplasia (MED) and pseudoachondroplasia (PSACH)." (PMID 25693198, 2015). "The retention of COMP in the rER lumen results in a novel form of oxidative stress in the chondrodysplasias, multiple epiphyseal dysplasia (MED) and pseudoachondroplasia (PSACH)." (PMID 28335520, 2017).
pseudoachondroplasia (continued). "This hypothesis was encouraged by the observation of phenotypic overlap with skeletal disorders in which either collagen type II or cartilage oligomeric matrix protein (COMP) is affected (spondyloepiphyseal dysplasia congenita and pseudoachondroplasia, respectively)." (PMID 38646780, 2024).
multiple epiphyseal dysplasia (50 papers, 2006 to 2025). Multiple epiphyseal dysplasias (MED/EDMs) are characterized by epiphyseal anomalies causing joint pain early in life, recurrent osteochondritis and early arthrosis. "Pseudochondroplasia is almost exclusively caused by COMP mutations, whereas various forms of multiple epiphyseal dysplasia have been attributed to mutations in the genes encoding COMP, type IX collagen COL9A1, COL9A2, and COL9A3chains and matrilin-3." (PMID 41009743, 2025). "Mutations in COL9 or COMP have been shown to cause multiple epiphyseal dysplasia (MED), which was a rare genetic disorder." (PMID 31346498, 2019). "Among them are pseudochondroplasia and multiple epiphyseal dysplasias, both of which are caused by mutations in the cartilage oligomeric matrix protein (COMP) gene." (PMID 31665048, 2019). "Heterozygous defects in COMP may result in multiple epiphyseal dysplasia, which is associated with mild growth disorders, hip and knee joint pain, swaying gait, and irregular epiphyseal ossification on imaging." (PMID 30541462, 2018). "Mutations in COMP result in protein misfolding causing two well-characterized skeletal dysplasias: PSACH and multiple epiphyseal dysplasia (MED)." (PMID 36835255, 2023). "Mutation in COMP also results in multiple epiphyseal dysplasia (MED; MIM# 132400), a relatively milder skeletal dysplasia and genetically heterogeneous disorder." (PMID 29104872, 2017). "Furthermore EDM1, another subgroup of multiple epiphyseal dysplasia, and pseudochondroplasia are linked to defects in cartilage oligomeric matrix protein (COMP) and share pathogenesis with EDM2, suggesting that COMP and CIX are interacting in the large polymeric network of cartilage." (PMID 16813664, 2006). "Nearby mutations in COMP, Cys348Arg, and Asp342Tyr, are designated as PSACH and severe multiple epiphyseal dysplasia (EDM1), respectively." (PMID 40291262, 2025). "Mutations on the Cartilage Oligomeric Matrix Protein (COMP) gene were subsequently found to cause PSACH and another skeletal dysplasia, multiple epiphyseal dysplasia." (PMID 21599986, 2011). "Here, we report the identification of two mutations in cartilage oligomeric matrix protein (COMP) that segregate with CTS in two large families with or without multiple epiphyseal dysplasia (MED)." (PMID 32686688, 2020). "Previous studies on COMP mutations have shown mutant COMP is co-localized with chaperone proteins, and we have reported an unfolded protein response (UPR) in mouse models of PSACH-MED (multiple epiphyseal dysplasia) harboring mutations in Comp (T585M) and Matn3, Comp etc (V194D)." (PMID 22006726, 2012). "Among the patients in categories 1–3 in this study, pathogenic variants were found in genes such as COL2A1, COMP, and MATN3, which are the causative genes of type II collagenopathy and multiple epiphyseal dysplasia (MED)." (PMID 34122524, 2021). "TSP-5/COMP is most highly expressed in cartilage and point mutations in its type 3 repeats and L-lectin domain are causal in pseudoanchrondroplastic dysplasia (PSACH) and some forms of multiple epiphyseal dysplasia (MED) (OMIM 117170 and 132400)." (PMID 16620379, 2006).
rheumatoid arthritis (48 papers, 2006 to 2025). A chronic, systemic autoimmune disorder characterized by inflammation in the synovial membranes and articular surfaces. "Studies in rheumatoid arthritis patients revealed that patients with serum levels of COMP <12 U/L are at a lower risk of joint destruction." (PMID 34884987, 2021). "We have developed a new mouse model for rheumatoid arthritis using COMP, where immunization with rat COMP is associated with development of autoimmune arthritis by cross-reactive immune response to autologous mouse COMP." (PMID 22906101, 2012). "Thus, it was concluded that serum COMP level may also serve as a biomarker in rheumatoid arthritis due to its association with disease activity and articular cartilage damage." (PMID 38791302, 2024). "For example, changes in the levels of some biomarkers like MMP-13 and COMP are also observed in other systemic diseases, such as rheumatoid arthritis, autoimmune disorders, and liver cirrhosis." (PMID 39911590, 2025). "Increased serum concentrations of COMP fragments have been reported for patients with knee osteoarthritis (OA) and early rheumatoid arthritis (RA)." (PMID 40943488, 2025). "Some studies have shown that COMP is a bone marker for knee osteoarthritis, hip osteoarthritis, and rheumatoid arthritis due to its correlation with cartilage destruction and matrix degradation." (PMID 34395611, 2021). "Recently, COMP is also thought as a biological marker for several diseases with high cartilage turnover rates such as rheumatoid arthritis and systemic sclerosis." (PMID 28129782, 2017). "Degradative fragments of COMP had been observed in diseased cartilage, synovial fluid, and serum of patients with posttraumatic knee injuries, primary osteoarthritis (OA), and rheumatoid arthritis (RA)." (PMID 26696755, 2015). "Measurement of intact COMP and fragments thereof in synovial fluid or serum correlates to cartilage destruction in rheumatoid arthritis (RA) and OA patient studies." (PMID 24886698, 2014). "Complexes between cartilage oligomeric matrix protein (COMP) and the complement activation product C3b have been found in the circulation of patients with rheumatoid arthritis and systemic lupus erythematosus." (PMID 24330664, 2013). "Another immunogenic adjuvant model of rheumatoid arthritis model is induced by cartilage-derived proteins such as collagen II, collagen XI and cartilage oligomeric matrix protein (COMP) in rat and mouse." (PMID 17391515, 2007). "In other studies, the feasibility of serum COMP as a prognostic indicator of future joint damage and as a marker of ongoing joint damage, e.g. in OA and rheumatoid arthritis, has been suggested." (PMID 17156423, 2006). "For instance, therapeutic interventions which aim at retarding joint damage, such as blockade of tumour necrosis factor- alpha in rheumatoid arthritis, normalize serum COMP levels." (PMID 17156423, 2006). "Furthermore, it has been shown that a low serum level of COMP, a cartilage turnover marker, predicts a good response to adalimumab therapy in rheumatoid arthritis." (PMID 40095875, 2025). "COMP is also present in rheumatoid arthritis, which makes it less specific for OA." (PMID 39076848, 2024). "The role of serum COMP concentrations has also been analyzed in patients with rheumatoid arthritis." (PMID 38791302, 2024). "Earlier, we developed a new mouse model for rheumatoid arthritis using COMP." (PMID 22906101, 2012). "To establish a rheumatoid arthritis model in C57BL/6 mice, we immunized C57BL/6NJ (B6N) mice with human cartilage oligomeric matrix protein (COMP), which induced severe arthritis with high incidence, accompanied by a strong auto-antibody response." (PMID 33708221, 2021). "Of note, the elevated baseline levels of COMP in marathoners were similar to those in OA, and the MIA levels were comparable to those in rheumatoid arthritis but higher than in OA." (PMID 34441422, 2021).
rheumatoid arthritis (continued). "Theophylline is an anti-inflammatory substance, and previous studies have shown that theophylline can reduce the levels of IL-6, COMP, JAK2, STAT3, RANKL, iNOS, and eNOS by modulating the JAK/STAT/RANKL signaling pathway, thereby alleviating the inflammatory response in rheumatoid arthritis." (PMID 37076836, 2023). "In this study, levels of MIA and the inflammatory biomarkers CRP, IL-1β, IL1-Ra, IL-6, sIL-6R, and TNF-α, and COMP were compared in marathoners, nonrunning healthy subjects, rheumatoid arthritis and OA patients." (PMID 34441422, 2021). "In patients with rheumatoid arthritis, acute lower body resistance exercise involving three sets of eight repetitions did not result in a significant increase in COMP." (PMID 31650307, 2019).
Arthritis (45 papers, 2007 to 2025). Inflammation of a joint. "COMP has been used as a diagnostic and prognostic indicator and as a marker of the arthritis severity and the effect of treatment." (PMID 41009743, 2025). "The mutational experiment resulted in a different profile of arthritis susceptibility, as the mutants COMP (COMP-F95S) resulted in eight-time reduction of incidence of arthritis." (PMID 33708221, 2021). "Recombinant COMP mutated at position 95 (COMP_F95S) lost its ability to induce arthritis or a strong immune response in the B6N mice." (PMID 33708221, 2021). "We conclude that antibodies to conformational epitopes are pathogenic and need for the induction of arthritis and that these antibodies are likely triggered by help from COMP specific T cell." (PMID 33708221, 2021). "Collectively, the role of ADAMTS-7 in the pathogenesis of arthritis is associated with degradation of COMP and upregulation of inflammatory cytokines and other metalloproteinases." (PMID 26696755, 2015). "COMP-C3b correlates with several inflammatory parameters describing mainly synovitis in RA, suggesting that joint inflammation causes the release of COMP fragments that are able to activate complement." (PMID 22264230, 2012). "The disease of arthritis and the need for a biomarker will be discussed, along with COMP and its value as a prognostic and diagnostic indicator." (PMID 19652761, 2009). "Further clinical and longitudinal studies of ethnic and other variations in serum COMP and its association with arthritis symptoms and functional status would be of benefit." (PMID 19652761, 2009). "COMP-deficient and wild-type mice were tested for onset, incidence, and severity of arthritis in both the collagen and collagen antibody-induced arthritis models." (PMID 19014566, 2008). "COMP deficiency led to early onset of the disease, with a mean onset of arthritis at 37.5 ± 2.81 days in COMP-deficient mice compared with 48.4 ± 13.7 days in the wild-type littermate group (P < 0.05)." (PMID 19014566, 2008). "COMP-deficient mice developed significantly more severe arthritis during the chronic phase of the disease course compared with wild-type mice." (PMID 19014566, 2008). "In the chronic phase of the disease course, the mean arthritis score in COMP-deficient mice continued to increase." (PMID 19014566, 2008). "This suggests that patients with short stature, delayed BA and a family history of early arthritis may have a COMP variant." (PMID 39415983, 2024). "COMP has been shown to be diagnostic of arthritis and to correlate with the disease severity." (PMID 19652761, 2009). "The role of ADAMTS-7 and ADAMTS-12 in the pathogenesis of arthritis was firstly supported by their ability to cleave COMP." (PMID 37651409, 2023). "The arthritis process was related to an increased serum COMP level, which was significantly reduced by both substances and their combination." (PMID 37373251, 2023). "Elevated levels of serum and synovial COMP have been detected in various forms of arthritis, such as RA, OA, and PsA." (PMID 37629227, 2023). "This study demonstrated that the CFA-arthritis group exhibited marked elevation in their COMP levels compared to the normal control group." (PMID 36678557, 2022). "The COMP immunization also induces a strong antibody response, which likely contributes to the development of arthritis." (PMID 33708221, 2021). "In summary, a new model for RA has been established using C57BL/6 (H-2b) mice through immunization with COMP, which is dependent on a COMP specific peptide, thus in similarity with collagen induced arthritis in H-2q (Aq) expressing strains." (PMID 33708221, 2021). "Our experiments provide a conclusive biochemical evidence that the Ab molecule binds COMP-P9 leading to COMP-specific T cell response in B6N mice, that is a key step for induction of arthritis." (PMID 33708221, 2021). "Pathologically, the upregulation of ADAMTS12 expression and cleavage of COMP by ADAMTS12 has been demonstrated in arthritis." (PMID 34093655, 2021).
Arthritis (continued). "The increased serum COMP and CRP levels in response to the underlying inflammatory condition is used as a biomarker for arthritis, including OA." (PMID 33776996, 2021). "The major T and B cell epitopes on COMP critically involved in the arthritis development were defined." (PMID 33708221, 2021). "Many of the mouse strains used developed severe arthritis with 3 antibodies, binding to collagen II, collagen XI, and cartilage oligomeric matrix protein (the Cab3 cocktail)." (PMID 32448385, 2020). "Antibodies to other cartilage proteins have also been investigated, and it has been found that antibodies to cartilage oligomeric matrix protein can induce arthritis." (PMID 32448385, 2020). "Polyclonal antibodies binding to COMP upon passive transfer induced arthritis, albeit at a lower level of severity as compared to CAIA." (PMID 29495570, 2018). "Animal results from surgically induced OA and collagen-induced arthritis models using ADAMTS-7 transgenic mice also supported the digestion of COMP by ADAMTS-7 in vivo." (PMID 26696755, 2015). "It is overexpressed in cartilage and synovium of arthritis patients, and the level of fragments of COMP in patients' serum is increased concurrently." (PMID 25653475, 2015). "It has been proved that ADAMTS-7 plays an important role in the pathogenesis of OA; it directly associates with and degrades COMP in vitro, and the level of ADAMTS-7 is elevated in cartilage patients with arthritis." (PMID 25653475, 2015). "Overexpression of ADAMTS-7 accelerated the degradation of COMP and the onset and progression of arthritis through formation of a positive feedback loop with TNF-α." (PMID 26696755, 2015). "COMP has been suggested as a candidate biochemical molecular marker of arthritis because of its relative specificity to joint tissues." (PMID 24964765, 2014). "Passive transfer of selected anti-COMP mAbs- enhanced arthritis when co-administered with a sub-arthritogenic dose of a mAb that specifically recognizes the J1 epitope of the CII molecule." (PMID 22906101, 2012). "Since we were interested in antibodies capable of inducing arthritis, we screened each antibody for its ability to bind autologous mouse COMP, a total of 18 mAbs reactive with rat COMP cross-reacted with mouse COMP." (PMID 22906101, 2012). "We have identified the specificities of mAbs to COMP and their contribution to the development of arthritis." (PMID 22906101, 2012). "Since cross-reactions with autologous COMP appear to be of importance for the development of arthritis, we analyzed the antibody reactivity to the autologous mouse recombinant full-length COMP and COMP fragments." (PMID 22906101, 2012). "We elucidated specificities of autoantibodies to COMP and its contribution to the development of arthritis." (PMID 22906101, 2012). "This experimental design was chosen because most of the COMP-specific mAbs are of the poorly complement-fixing IgG1 isotype, and complement activation is one of the critical factors for development of arthritis." (PMID 22906101, 2012). "Passive transfer of COMP-specific mAbs enhanced arthritis when co-administrated with a sub-arthritogenic dose of a mAb specific to collagen type II." (PMID 22906101, 2012). "Here we clearly show that arthritogenic antibodies are indeed produced after native COMP immunization that are preferentially directed to the EGF region of the COMP molecule, bind cartilage and induce arthritis in naïve mice." (PMID 22906101, 2012). "ADAMTS12 was first reported to be important in arthritis because of its ability to bind and degrade the cartilage oligomeric matrix protein (COMP)." (PMID 24213506, 2012). "In COMP+/+Ncf1*/* mice, the incidence of arthritis was 80% with the day of disease onset at 36 to 38 days." (PMID 22906101, 2012).